LEP (leptin)
Diseases named in the same sentence as LEP in open-access papers (continued):
Sharing a sentence is not in itself a finding about the gene and the disease.
Infertility (continued). "In the preovulatory phase (12th day) of the cycle, infertile subjects with body mass index (BMI) <20 and 20-24.9 had significantly higher values for leptin (p<0.05), whereas, with an increase in BMI, leptin levels were reduced in these females." (PMID 32025443, 2019). "Leptin was reduced further in the luteal phase of infertile females with BMI 25-30, with a significantly lower value for FSH (p<0.005), LH (p<0.005), and estradiol (p<0.005." (PMID 32025443, 2019). "In general, leptin-resistant genotypes are affected by low reproductive efficiency, with affected individuals being prone to infertility." (PMID 30288483, 2018). "The second study involved 42 infertile patients with varicocele ([leptin] = 3.01 ng/mL) compared to 10 control men ([leptin] = 1.79 ng/mL)." (PMID 29971101, 2018). "Follicular fluid leptin levelin all subgroups of explained infertile group was lower as compared to unexplainedand fertile women." (PMID 26246872, 2015). "For this, various studieshave already been performed to discover thecauses of infertility, among them high leptin levelhas been considered as one of the important andeffective factors in several studies." (PMID 26246872, 2015). "In regard to mean serum leptin,explained infertile women had higher mean serumleptin level (33.13 ± 17.31) compared to unexplainedinfertile women (27.83 ± 25.29) and fertilewomen (31.27 ± 11.02), but the difference wasnot significant (P=0.070)." (PMID 26246872, 2015). "The aim of this study was to compare serum andfollicular fluid leptin concentrations among explainedinfertile women, unexplained infertile women andfertile women in order to find the role of leptin levelin infertility." (PMID 26246872, 2015). "Follicular fluid and serum leptin levels in theeach subgroup of explained infertile women weredetermined and the results were compared withunexplained infertile and fertile woman." (PMID 26246872, 2015). "The results suggested that high leptin level of follicular fluid is one of themain factors involved in infertility." (PMID 26246872, 2015). "The aim ofthis stduy is to compare serum and follicular fluid leptin concentrations in order to findthe role of leptin level in infertility." (PMID 26246872, 2015). "The obtained results showed that high leptin levelin follicular fluid affect unexplained infertility.Therefore, our finding suggested that high leptinlevel of follicular fluid is one of the main factorsinvolved in infertility." (PMID 26246872, 2015). "We found significantly lower serum and FF-leptin levels in NOW-PCOS compared to BMI-matched infertile women and a positive correlation between insulinemia and FF-leptin levels in NOW-PCOS only." (PMID 24895638, 2014). "This study was designed to compare the expression of leptin and its receptors in ovarian tissue affected by endometrioma in infertile women to its expression in the normal ovarian tissue of fertile controls not affected by endometriosis." (PMID 24401660, 2014). "PF leptin levels were significantly higher in infertile women with endometriosis than in patients with pelvic pain and endometriosis or unexplained infertility." (PMID 24401660, 2014). "In a subgroup of endometriosis patients presenting pelvic pain, a positive correlation was found between peritoneal fluid leptin concentration and severity of symptoms, except when infertility was the main presenting symptom." (PMID 23634146, 2013). "Leptin knockout (ob/ob) or leptin receptor knockout (db/db) mice display reproductive deficits and infertility." (PMID 22132231, 2011). "Decreases in leptin, which are sensed as starvation, trigger a constellation of adaptive responses including increases in appetite, decreases in energy expenditure, infertility, reduced immune function, and development of a euthyroid sick state." (PMID 21853117, 2011).
Infertility (continued). "Leptin influences kisspeptin neuron activity, indirectly regulating gonadotropin-releasing hormone and affecting the hypothalamic-pituitary-ovarian axis, which in turn impacts ovulation and uterine function, potentially leading to infertility." (PMID 39815248, 2025). "Hence, at present, we can only hypothesize that leptin might contribute to pelvic inflammation in endometriosis, potentially altering the local microenvironment of the peritoneal cavity, yet its direct impact on endometriosis-associated infertility is uncertain." (PMID 38567305, 2024). "This crosstalk of leptin- kisspeptin has also been seen in infertile males." (PMID 38356829, 2024). "Leptin affects LEPR receptors in the hypothalamus, crossing the blood–brain barrier, but also affects NLPR3 receptors in the ovary, associated with ovulation, thus inhibiting follicle development and leading to infertility." (PMID 39797110, 2024). "The influence of leptin on the hypothalamic–pituitary–gonadal (HPG) axis has been well recognized: patients with leptin signaling defects exhibit delayed puberty and some degree of infertility, with promising results shown in studies using recombinant leptin for treatment." (PMID 39797240, 2024). "A major finding of our study was that leptin levels of MetS+ infertile patients were higher than the MetS− infertile patients and HCs, suggesting that elevated serum leptin levels may be related with MetS and semen parameters in infertile patients." (PMID 39496062, 2024). "Further analysis showed that those findings were related to poor IVF outcome, suggesting that abnormalities of leptin secretion and signaling pathway could be involved in PCOS-associated infertility." (PMID 37493841, 2023). "Leptin administration can rescue the infertility phenotype of ob/ob mice." (PMID 36138127, 2022). "We found that serum or seminal leptin was higher in infertile males than that in fertile ones." (PMID 36213199, 2022). "In addition, sperm count (SMD = −4.533, 95% CI: −6.565, −2.501) and sperm motility (SMD = −7.894, 95% CI: −10.616, −5.172) inversely correlated with leptin levels in infertile males." (PMID 36213199, 2022). "Significantly elevated leptin concentrations were observed in infertile male patients." (PMID 36213199, 2022). "This study was performed based on published articles related to leptin and infertile males." (PMID 36213199, 2022). "Moreover, leptin level was significantly higher in PCOS-infertile (33.27±8.45 ng/ml) and PCOS-RPL (36.47±7.41 ng/ml) sub-groups compared to the non-PCOS group." (PMID 34407095, 2021). "It has been demonstrated on obese mice lacking leptin gene that the absence of functional leptin may lead to suppressed gonadotropin secretion, which results in infertility, whereas exogenous leptin treatment restores fertility in the obese mice." (PMID 35054403, 2021). "In humans, compared to the normal women, the infertile women with polycystic ovary syndrome have increased serum kisspeptin levels, and serum kisspeptin has a positive correlation with the serum levels of LH and leptin." (PMID 30759773, 2019). "As serum E2 has a significant correlation with leptin in infertile subjects, it is likely that an increased fat mass may play some role in establishing a relationship between serum estradiol and serum leptin." (PMID 32025443, 2019). "AgRP/NPY neurons are a direct target of leptin, and they play roles in leptin-associated infertility under negative energy balance conditions." (PMID 29976877, 2018). "LEP-2548G/A genotype is different between fertile and infertile patients (p = 0.012)." (PMID 29971101, 2018). "Given the function of blood testis barrier in maintaining normal spermatogenesis, leptin-induced blood testis barrier impairment may be one of the mechanisms contributing to male subfertility and infertility." (PMID 29855380, 2018).
Infertility (continued). "We studied specific glycan synthesis, leptin system and inflammatory gene expression in white blood cells as potential biomarkers of infertility in 54 adults with CG adults (27 females and 27 males) (age range 17–51 yr) on a galactose-restricted diet in a multi-site Irish and Dutch study." (PMID 30231941, 2018). "Thus, comparing two groups (obese fertile versus infertile men), an Egyptian team observed circulating concentrations of leptin higher in the infertile group compared to the fertile group." (PMID 29971101, 2018). "Serum leptin levels are augmented in obese infertile men and in men with azoospermia." (PMID 29855380, 2018). "Therefore, we wanted to identify Kisspeptin-Leptin association with body mass index (BMI) and success of assisted reproductive treatments (ART) in infertile females." (PMID 29805405, 2018). "Deregulation of leptin levels might be responsible for some reproductive problems such as infertility; however, little is known regarding long-term effects of early stress and modifications in leptin levels on female reproduction." (PMID 26759712, 2016). "It seems that leptin is one ofthe involved factors in infertility." (PMID 26246872, 2015). "The results of our study showed significant higherfollicular fluid leptin level in unexplained infertilewomen compared to the explained infertile andfertile groups, but serum leptin level in this groupwas insignificantly lower than the explained infertileand fertile groups." (PMID 26246872, 2015). "The possibility exists that too low levels of FF-leptin decrease fertility in NOW-PCOS women as well as too high FF-leptin levels might favor infertility in overweight/obese PCOS women." (PMID 24895638, 2014). "Additionally, higher and lower levels of leptin are also related with infertility but the mechanism of involvement is still undiscovered." (PMID 25587271, 2014). "Due to the infertility of the ob/ob mice and the complete rescue of fertility following leptin administration, leptin was initially hypothesized to be the key signal for the onset of puberty." (PMID 22851226, 2013). "Accumulating evidence suggests that increased leptin levels contribute to the pathogenesis of reproductive abnormalities including infertility, polycystic ovary syndrome (PCOS), anovulation, disruption of the menstrual cycle, hyperinsulinemia and many other conditions." (PMID 19849856, 2009). "However, leptin resistance could contribute to infertility by counteracting the kisspeptin/KissR system activity in patients with T2DM." (PMID 35432804, 2021). "Theob/ob mice (lacking functional leptin with mutation in leptin gene) are infertile." (PMID 24696768, 2014). "Chou and Mantzoros stated that even though leptin concentration has no major role in the hypothalamic–pituitary–gonadal axis and consequently in the regulation of ovarian function, as it is directly correlated with BMI, it may indirectly cause infertility." (PMID 38673534, 2024). "In the PCOS group (with infertility and RPL), plasma leptin was significantly higher and sOB-R much lower in comparison to non-PCOS controls." (PMID 38027110, 2023). "In this study, we investigated for the first time the level of leptin and sOB-R and the frequency of rs7799039 and rs1137101 SNPs in PCOS-infertile and PCOS-RPL women." (PMID 34407095, 2021). "The present study showed a significantly higher level of free leptin in the PCOS group and also infertile and RPL subgroups as compared to the healthy subjects." (PMID 34407095, 2021). "Plasma leptin and sOB-R levels were significantly higher and lower in PCOS, PCOS-infertile and PCOS RPL groups, respectively." (PMID 34407095, 2021). "Normalization of stromal proteins expression of IGF-1R and LEP in obese mice ovaries may be essential for reversion of androgenic medium, hormonal equilibrium, in the body weight regulation and the glycose metabolism, and, therefore, the regulation of obese/infertility phenotype of this model." (PMID 29430464, 2017).
Infertility (continued). "Thus, resistance to insulin or leptin in Kiss1 neurons could lead to infertility." (PMID 25946091, 2015). "Thus, the presence of infertility associated with endometriosis does not seem to influence leptin concentrations, but leptin might play a role in thepathophysiology of pain associated with endometriosis." (PMID 23634146, 2013). "In male ob/ob mice, the absence of leptin results in infertility, which can be restored with leptin therapy." (PMID 41463076, 2025). "Female mice lacking leptin are infertile; however, the administration of leptin (5 mg/kg twice daily) only during implantation—i.e., the first 6 days of pregnancy—leads to normal pregnancy and parturition." (PMID 39201703, 2024). "Conversely, in the subgroup without infertility, the level of leptin/BMI in PF was marginally higher in the study group than in the control group." (PMID 38567305, 2024). "Leptin was chosen since studies had demonstrated that mice lacking the expression of leptin (ob/ob) or its receptor (db/db) are infertile and have severely underdeveloped mammary tissue." (PMID 37686154, 2023). "Significantly higher serum concentrations of leptin, FSH, and LH were found in infertile males." (PMID 36213199, 2022). "It has been suggested that high leptin in PCOS may interfere with the development of the mature oocyte and ovarian steroidogenesis, contributing to ovulatory dysfunction and infertility." (PMID 35355566, 2022). "Leptin, an anorexigenic peptide produced by white adipose tissue, inhibits hypothalamic ES, and Ob/Ob mice, lacking leptin, over-activate the hypothalamic endocannabinoid signalling and are affected by infertility due to hypogonadotropic hypogonadism." (PMID 32046164, 2020). "The present study highlighted the effects of exogenous leptin on sperm parameters and the role of leptin in damaging BTB integrity, which could be a mechanism for leptin-related male subfertility and infertility." (PMID 29855380, 2018). "Animals lacking functional leptin or its receptor show marked suppression of pulsatile LH secretion and are infertile." (PMID 27215137, 2016). "In explained infertile group, mean follicular fluidleptin level (19.92 ± 17.87) was lower than meanserum leptin level (33.13 ± 17.31), but the differencewas not significant (P=0.11)." (PMID 26246872, 2015). "The present study suggested that high level offollicular fluid leptin has a negative effect on reproductionin unexplained infertility." (PMID 26246872, 2015). "In explained infertile and fertile groups, as opposed to unexplained infertilegroup, mean leptin level was lower in follicular fluid than in serum." (PMID 26246872, 2015). "At the same time, adipokines from adipose tissue could cause low testosterone levels (as occurs with the negative feedback of leptin) and increased inflammation and thus contribute to infertility." (PMID 39396139, 2024). "Furthermore, extreme leptin resistance and consequent low or absent leptin signalling resembles a state of starvation and can thus lead to infertility." (PMID 34502119, 2021). "However, the exact role of leptin and sOB-R in the development of infertility and RPL in women with PCOS is not fully clear." (PMID 34407095, 2021). "Consequently, POMC neurons as a target of leptin/insulin actions were shown to be important for fertility, as IR/LEPR-POMC KO mice exhibit lengthened reproductive cycles, follicular arrest, hyper-androgenemia, and infertility." (PMID 27146259, 2016). "The total number of samples which assessed for leptin and leptin receptor levels was 177 (non-PCOS = 49, PCOS-RPL = 70 and PCOS-infertile = 58)." (PMID 34407095, 2021). "In conclusion, this study showed a significantly higher level of leptin and lower level of sOB-R in the PCOS group as well as PCOS-infertile and PCOS-RPL subgroups in comparison with non-PCOS women." (PMID 34407095, 2021).
Infertility (continued). "A significant reverse correlation existed between plasma levels of leptin and sOB-R in non-PCOS (r = -0.289, P = 0.044) subjects and PCOS females with infertility (r = -0.382, P = 0.003) or RPL (r = -0.447, P<0.001)." (PMID 34407095, 2021). "This study aims to compare infertile women with and without PCOS regarding serum levels of leptin and several other hormones." (PMID 29177243, 2017).
liver fibrosis (106 papers, 2007 to 2026). "Particularly, leptin deficiency causes impaired liver regeneration in ob/ob mice, and altered cytokines expression is associated with impaired hepatic fibrosis in response to CCl4 treatment." (PMID 39832399, 2025). "Serum leptin has a pro-inflammatory effect, and hyperleptinemia promotes the development of hepatic fibrosis, leading to the development of MASLD associated with lipotoxicity." (PMID 39767635, 2024). "Another well-known model, the ob/ob (leptin-deficient) mouse model, can hardly develop hepatic fibrosis when fed on CD." (PMID 38507181, 2024). "Leptin-deficient (ob/ob) mice and Leptin receptor-deficient (Zucker) rats are widely used for studying the mechanisms underlying the role of Leptin in hepatic fibrosis." (PMID 37705071, 2023). "The LEPTIN deficient pigs generated in this study mirror the progression of hepatic fibrosis observed in NAFLD patients." (PMID 37705071, 2023). "Adipokines such leptin and adiponectin have been implicated to hepatic fibrosis, orbital fibrosis and lung fibrosis." (PMID 36295095, 2022). "In this study, hepatic fibrosis in leptin-deficient ob/ob mice was more pronounced than in the C57BL/6J and KK-Ay mice when administered the FFD regime." (PMID 31023717, 2019). "Leptin also increases hepatic fibrosis, whereas a deficiency of leptin is related to the decreased hepatic injury in animal models." (PMID 24733068, 2014). "In a previous study, AMPK activation attenuating leptin-mediated hepatic fibrosis is associated with inhibition of STAT3 activation." (PMID 25188319, 2014). "It is also well recognized, that in the other tissue, such as the liver, leptin promotes the activation of locally resident fibroblasts and leptin production associates with liver fibrosis." (PMID 21829567, 2011). "Furthermore, leptin administration accelerates CCl4-induced hepatic fibrosis but reduces fibrosis in leptin-deficient ob/ob mice." (PMID 39832399, 2025). "In conclusion, we demonstrate that CCl4-induced hepatic fibrosis was closely associated with hepatic inflammation, oxidative stress, apoptosis, and autophagy, but these adverse effects were less severe in leptin-deficient ob/ob mice than in WT mice through downregulating LCN2-related signaling." (PMID 39832399, 2025). "Conversely, there is evidence showing that activated HSCs reciprocally contribute to leptin expression and subsequent exacerbation of liver fibrosis; in contrast, quiescent HSCs have been found to be associated with higher expression of adiponectin and low levels of leptin." (PMID 33316927, 2020). "Leptin, a cytokine primarily produced by adipose tissue, has been linked to hepatic fibrosis." (PMID 26761430, 2016). "Thus, leptin levels are associated with hepatic steatosis severity and degree of liver fibrosis." (PMID 40985048, 2025). "Likewise, miR122 inhibited leptin-induced liver fibrosis in the leptin-deficient mouse model." (PMID 33316927, 2020). "We compare the performance of simple biochemical scores (FIB-4 and APRI) with leptin and vitamin D. Also, We identified the proteins in the serum of liver fibrosis and showed the role of these proteins in the pathogenesis of liver fibrosis." (PMID 41721256, 2026). "RESULTS: We found that serum leptin levels and APRI values were significantly higher in liver fibrosis patients than in controls, after three- and six-months following LT serum leptin levels and APRI values significantly decreased." (PMID 41721256, 2026). "Adipokines such as TNF-α, leptin, and resistin can be disrupted by lower levels of thyroid hormone in circulation, exacerbating liver fibrosis." (PMID 40006040, 2025). "The mechanisms by which adipose-derived hormones such as adiponectin and leptin signal to the liver, thereby regulating hepatic insulin sensitivity and liver fibrosis, are also essential." (PMID 40985048, 2025).